MYCN (MYCN proto-oncogene, bHLH transcription factor)
Diseases named in the same sentence as MYCN in open-access papers (continued):
Sharing a sentence is not in itself a finding about the gene and the disease.
retinoblastoma (continued). "Interestingly, in 2013, it was recognized that a rare, non-heritable, aggressive form of retinoblastoma is actually driven by high-level MYCN amplification with normal RB1 genes." (PMID 31683923, 2019). "Hence, pRb inactivation, through mutation, phosphorylation or some other as yet unknown mechanism, is likely to be the initiating event in retinoblastoma tumorigenesis with or without MYCN amplification." (PMID 28211617, 2017). "Apart from the previously reported very young age of diagnosis for RB1-proficient retinoblastoma, we did not observe differences in gene expression, chromosomal or genetic features between the RB1−/− and RB1-proficient MYCN-amplified retinoblastomas." (PMID 39079981, 2024). "The vast majority of retinoblastomas initiate with biallelic inactivation of RB1 and a small subset (1–2%) initiate with MYCN amplification in the absence of RB1 inactivation." (PMID 34315877, 2021). "An uncommon subgroup of unilateral retinoblastomas with highly aggressive histological features, lacking aberrations in RB1 gene with high-level amplification of MYCN (MCYNamplRB1+/+) has only been described as intra-ocular cases treated with initial enucleation." (PMID 32971811, 2020).
prostate carcinoma (67 papers, 2012 to 2026). A carcinoma that arises from epithelial cells of the prostate gland. "Both MYC and MYCN directly upregulate enhancer of zeste homolog 2 (EZH2) which is linked to prostate cancer progression." (PMID 28212321, 2017). "Genetic instability has been linked to MYCN and more specifically 14% of all prostate cancers have MYCN-amplifications." (PMID 28358317, 2017). "Dysregulation of the MYCN gene correlates with the development of various other cancer types, such as breast cancer, small-cell lung cancer, prostate cancer, basal cell carcinoma, acute lymphoblastic leukemia, and glioblastoma." (PMID 39802403, 2025). "The overexpression of MYCN is not limited to gliomas, including astrocytoma, meningioma, and glioblastoma, but is also detected in various other cancer types, including prostate cancer, hematological malignancies, lung cancer, and pancreatic cancer." (PMID 39802403, 2025). "In prostate cancer, MYCN enhances tumor progression by transcriptionally activating genes such as PARP1 and BRCA1." (PMID 40593489, 2025). "Mechanistically, CHRM4-driven AKT/MYCN signaling upregulated the interferon alpha 17 (IFNA17) cytokine in the prostate cancer TME after ADT." (PMID 37142586, 2023). "We found that increased IFNA17 protein expression was associated with induction of CHRM4, phosphorylated (p)-AKT, and MYCN proteins in prostate cancer cells, but decreased expression of these proteins was observed after DHT treatment." (PMID 37142586, 2023). "IFNA17 mediates a feedback mechanism in the TME by activating the CHRM4/AKT/MYCN signaling-driven immune checkpoint pathway and neuroendocrine differentiation of prostate cancer cells." (PMID 37142586, 2023). "Abundant CHRM4-driven AKT/MYCN signaling upregulates interferon alpha 17 (IFNA17) cytokine activity in prostate cancer after ADT." (PMID 37142586, 2023). "MYCN-driven PDL1 was significantly elevated when prostate cancer cells were cultured under ADT conditions or with IFNA17 treatment, and its expression decreased after CHRM4-KD." (PMID 37142586, 2023). "Concurrent ALK and MYCN gene amplifications contribute to the activation of Wnt/β-catenin signaling pathway in a synergistic manner, leading to the progression of prostate cancer to NEPC." (PMID 35633416, 2022). "A study aimed at understanding the MYCN-triggered epigenetic reprogramming of prostate cancer to neuroendocrine prostate fate, the cistrome, and the transcriptome of these tumours were investigated in vitro, in vivo, and in patient-derived organoids." (PMID 34445233, 2021). "In conclusion, MYCN-driven prostate tumours displayed greater aggressiveness, with MYCN driving transcriptional programmes in advanced stages of prostate cancer." (PMID 34445233, 2021). "The study of a large set of treatment-related NEPCs showed AURKA amplification in 65% of primary prostate cancers and 86% of metastases and concurrent MYCN amplification was detected in 69% of treated prostate cancers and 83% of metastases." (PMID 31366128, 2019). "A positive feedback loop has been described whereby AURKA induces MYCN and it has therefore been suggested that this cooperation leads to the prostate cancer phenotype." (PMID 28358317, 2017). "MYCN has been shown to repress androgen receptor signaling in prostate cancer and can redirect the binding of the transcription factor enhancer of zeste homolog 2 (EZH2) to the MYCN promoter resulting in gene silencing." (PMID 28358317, 2017). "Recent molecular characterization of NEPC showed up-regulation of AURKA and MYCN expression and co-operative function to induce neuroendocrine differentiation in prostate cancer cells." (PMID 27015368, 2016).
prostate carcinoma (continued). "MYCN overexpression leads to the development of poorly differentiated, invasive prostate cancer." (PMID 38887275, 2024). "Conversely, certain experiments indicate that NEPC undergoes transdifferentiation from prostatic adenocarcinoma, supported by the detection of prostate cancer-specific mutations (for example, ERG rearrangements) and gene amplifications (for example, AURKA and MYCN) in both subtypes." (PMID 38534956, 2024). "Furthermore, a phase 2 study indicated that amplification of AURKA and/or MYCN in prostate cancer conferred sensitivity to Aurora kinase A inhibition." (PMID 37025467, 2023). "Therefore, we examined the impact of ELAVL3 overexpression in prostate cancer cell lines and discovered that it effectively stimulated the expression of neuroendocrine markers, alongside MYCN, NCAM1, and SYP when compared with vector control." (PMID 38016952, 2023). "MYC dysregulation appeared to be tissue-specific tissue during tumorigenesis; MYCN was described to be aberrantly expressed in neuronal or neuroendocrine tumors, and more recently, in ovarian cancer, prostate cancer, and in a subset of breast cancer with poor prognosis." (PMID 36983070, 2023). "We hypothesized that ADT-induced abundance of the MYCN transcription factor in prostate cancer cells might allow it to bind to the E-box on the IFNA17 regulatory sequence." (PMID 37142586, 2023). "Analysis of CHRM4-driven IFNA17 cytokine release in the prostate cancer TME following ADT resistance may provide a clear understanding of the feedback loop consisting of CHRM4/AKT/MYCN in the context of AR inhibition." (PMID 37142586, 2023). "Interestingly, MYCN has been shown to drive NE prostate cancer initiation, as it can epigenetically activate neural lineage gene expression in prostate cancer." (PMID 37255415, 2023). "AR expression in normal prostate tissues may inhibit CHRM4 expression; however, AR inhibition in advanced prostate cancer after ADT may lead to CHRM4/AKT/MYCN activation, which in turn promotes the NED and invasiveness of prostate cancer cells." (PMID 37142586, 2023). "In our previous study, we found that stimulation of the muscarinic acetylcholine receptor 4 (CHRM4)/AKT/MYCN pathway may lead to the development of NEPC in prostate cancer after ADT." (PMID 37142586, 2023). "For instance, MYCN-driven, castration-dependent prostate cancer may progress towards a neuroendocrine fate through lineage plasticity and epigenetic reprogramming, reducing therapy efficacy." (PMID 34445233, 2021). "The mechanisms of the MYCN-mediated repression of CDKIs are unclear; while MYCN associates more weakly with the MIZ1 repressor when compared to MYC, at least in the context of prostate cancer, MYCN can also bind and recruit the PRC2 histone methylase to repress target genes." (PMID 33092025, 2020). "c-Myc, a well-known oncogene, has been reported to cooperate with family members MYCN and MYCL to promote the tumorigenesis of prostatic cancer." (PMID 34657603, 2021). "In 2011, Beltran and coworkers reported the frequent gene amplifications of MYCN and AURKA occurring in 40% of NEPC and 5% of prostate cancer adenocarcinomas, conferring a pronounced sensitivity of tumor cells to Aurora kinase inhibitors." (PMID 31366128, 2019). "CNAs at the level of MYC, MYCN, GSK3B, MTOR, and BRCA2 are more frequently detected in germline BRCA2-mutant prostate cancers than in sporadic localized cancers." (PMID 31366128, 2019). "c-MYC (MYC) is a well-established oncogene and along with family members MYCN and MYCL are significant in driving tumorigenesis in prostate cancer." (PMID 28212321, 2017). "During treatments targeting the androgen receptor, MYCN promotes changes of cancer origin from epithelial to neuroendocrine, which suggests that MYCN can contribute to the NEPC phenotype and drug resistance of prostate cancer." (PMID 39802403, 2025).
prostate carcinoma (continued). "Mechanistically, MYCN promoted miR‐421 upregulation, consequently enhanced ATM expression and its phosphorylation, and then alleviated the senescence of castration‐resistant C4‐2 prostate cancer cell." (PMID 39372390, 2024). "Furthermore, MYCN and Aurora Kinase A (AURKA) have higher expression in late stage neuroendocrine prostate cancer than other prostate cancer types and they have been suggested to cooperate in inducing differentiation." (PMID 28358317, 2017). "Our findings suggest that ADT-induced CHRM4 may activate AKT/MYCN signaling to induce IFNA17 secretion and upregulate immune checkpoints in the TME to drive potential immunosuppressive responses, leading to NED and metastasis in prostate cancer." (PMID 37142586, 2023). "Furthermore, transcriptional profiling of MYCN-expressing 22Rv1 prostate cancer xenograft models in castrated and non-castrated states revealed that castration led to an increase in expression of neural lineage genes (e.g., SOX11)." (PMID 34445233, 2021). "MYCN is not usually expressed in the epithelial lineage that gives rise to prostate cancer." (PMID 34445233, 2021). "It is common for a NE prostate cancer phenotype to not express AR and PSA and common for amplification of the genes aurora kinase A (AURKA) and N-myc (MYCN, both of which were overexpressed in ACRJ-PC28 at RNA-seq level and MYC was detected at the protein level." (PMID 36643868, 2022).
breast carcinoma (63 papers, 1989 to 2026). "Additionally, increased MYCN has been associated with the metastatic properties of breast cancer." (PMID 39802403, 2025). "Additionally, we identified the alterations of epigenetic targets, such as SWI/SNF related genes (SMARCA2, SMARCA4, SMARCA5) or histone modifiers (KMT2C or KMT2D), breast cancer-associated oncogenes (MYCN or MAPKs), or genes that are involved in drug-resistance (ESR1 and PIK3CA/B)." (PMID 31216647, 2019). "Research indicates that the MYC family, including MYCN, correlates with breast cancer tumorigenesis, particularly in triple-negative breast cancer (TNBC)." (PMID 40862719, 2025). "Treatment with buparlisib (PI3Kα/β/δ/γ inhibitor) reduced the expression of Wnt target genes AXIN2, LEF1, and MYCN in human PIK3CA-mutant ER+ breast cancer cells." (PMID 37471270, 2023). "While BUB1, KRT5, and MYCN were overexpressed in young women with breast cancer, CXCL12 showed a decreased expression." (PMID 36685821, 2022). "Meanwhile, IGF2BP1/MIR210HG/miR-210 regulatory axis mediates the tumorigenesis role of MYCN in breast cancer." (PMID 35346372, 2022). "In this study, we revealed that CHD7 likely regulates a small set of oncogenes, such as NRAS and MYCN, in breast cancer." (PMID 28649742, 2017). "For example, MYC and MYCN genes regulate the expression of miR-9 in breast cancer, and DNA methylation influences miR-9 expression in colorectal cancer." (PMID 27917340, 2016). "For instance, MYC/MYCN regulates the expression of miR-9 in breast cancer, and DNA methylation influences miR-9 expression in colorectal cancer." (PMID 24969351, 2014). "MYCN expression correlates with the clinical stage and outcome of patients with breast cancer." (PMID 39802403, 2025). "Hence, IGF2BP1-MIR210HG/miR-210 axis provides an alternative explanation that MYCN is an oncogene in breast cancer." (PMID 35346372, 2022). "In addition, clinical relevance data showed that MIR210HG expression was positively correlated to MYCN expression in breast cancer." (PMID 35346372, 2022). "In addition, the expression of IGF2BP1 was identified positively correlated to MYCN expression in breast cancer." (PMID 35346372, 2022). "The MYCN/IGF2BP1/MIR210HG axis may serve as an alternative molecular mechanism of breast cancer progression." (PMID 35346372, 2022). "Furthermore, CYP26A1 was found to be a retinoid-responsive gene in retinoid-sensitive NB in MYCN transgenic mice and lung and breast cancer cell lines." (PMID 36231133, 2022). "The upstream region of MYCN, which may play a regulatory role in MYCN expression, was associated with GMD expression in breast cancer and in COAD/READ." (PMID 33676569, 2021). "Moreover, miR-9, which is directly bound and upregulated by MYC and MYCN in breast cancer cells, directly targets CDH1, leading to increased cell motility and invasiveness." (PMID 31208279, 2019). "In breast cancer, the gene expression profile of tumors with FDG SUVmax > 10 showed an “FDG signature” that was enriched with glycolysis-related genes and associated with activation of the MYC transcription factor (c-Myc), a functional counterpart of MYCN." (PMID 26959748, 2016). "In addition, a previous study has shown that miR-9, which is directly bound and upregulated by MYC and MYCN in breast cancer cells, directly targets CDH1, leading to increased cell motility and invasiveness." (PMID 24520301, 2014). "Therefore, the MYCN/IGF2BP1/MIR210HG axis may serve as an alternative molecular mechanism of breast cancer progression." (PMID 35346372, 2022). "Therefore, combining previous studies, MYCN is an oncogene in breast cancer." (PMID 35346372, 2022). "We also found EGFR, MYCN, and MYC in brain cancers;39,40BCL2, MYC, and the loci of IGH translocations in lymph-nodes cancer;41–43CDK12 in breast cancer; CCND1 in liver cancer; and RUNX1, GATA6, and PDE4D in esophageal cancer." (PMID 36163358, 2022).
breast carcinoma (continued). "In summary, MYCN functions as a transcription factor of IGF2BP1, which induces IGF2BP1 expression and promotes breast cancer progression." (PMID 35346372, 2022). "Our independent analysis of primary ER+PIK3CA-mutant breast cancers, which exhibit high INPP4B expression, identified these and additional upregulated Wnt genes (LEF1, MYCN, FZD7, SFRP2, TCF7L1, CTNNB1, FZD4, and SFRP1)." (PMID 34035258, 2021). "Our data may also be applicable to MYCN signaling pathways in other cancers in which RB1 inactivation occurs, including lung, ovarian and breast cancers." (PMID 39079981, 2024). "PIK3CA mutant ER+ breast cancers exhibit an RNA expression profile of enhanced Wnt/β-catenin signaling, including up-regulation of Wnt target genes (AXIN2, LEF1, MYCN) and other components such as transcriptional regulators (TCF7L1, TCF7L2, CTNNB1), receptors (FZD4, FZD7) and ligands (WNT5A)." (PMID 37471270, 2023). "Mycn amplification has also been observed in rat tumors, specifically in uterine endometrial carcinomas, however, the available literature does not include any investigation of MYCN amplification status in breast cancer." (PMID 22253826, 2012). "Interestingly, in some tumors with non-amplified MYCN (breast cancer, Wilms tumor), TSSC1 behaves as a tumor suppressor gene instead of an oncogene." (PMID 34830942, 2021). "Furthermore, expression of the classical breast cancer oncogenes EGFR (epidermal growth factor receptor) and v‐Myc avian myelocytomatosis viral oncogene neuroblastoma‐derived homolog (MYCN) was also positively correlated with CHD7 expression, with Spearman's r = 0.24 and 0.12, respectively." (PMID 28649742, 2017).